PTPN2 (protein tyrosine phosphatase non-receptor type 2)
Diseases named in the same sentence as PTPN2 in open-access papers (continued):
Sharing a sentence is not in itself a finding about the gene and the disease.
tumor (96 papers, 2007 to 2026). "Targeting patient-specific mutations in key regulatory genes such as PTPN2 or NF-κB using CRISPR/Cas9 gene editing technology can lead to the knockout of specific proteins in tumor cells." (PMID 38362491, 2024). "Previous studies have shown that loss of PTPN2 in tumour cells enhances the response to immunotherapy by sensitizing tumours to IFNγ3." (PMID 37794185, 2023). "Like Ptpn2, Fitm2 loss has previously been shown to sensitize tumor cells to T cell-mediated killing." (PMID 38052854, 2023). "We compared the effect of PTPN2/N1 inhibition to genetic deletion and found that AC484 dose-dependently enhanced IFNγ-driven growth arrest in vitro, comparable to Ptpn2/n1-deficient B16 tumour cells." (PMID 37794185, 2023). "To this end we implanted AT3-OVA tumor cells into the inguinal mammary fat pads of floxed control versus Lck-Cre;Ptp1bfl/fl or Lck-Cre;Ptpn2fl/fl T cell-specific PTP1B- or PTPN2-deficient female mice respectively and monitored tumor growth." (PMID 37500611, 2023). "Transcriptomic profiling revealed that AC484-treated and Ptpn2/n1-deficient tumour cells had highly similar global transcriptional responses to IFNγ treatment." (PMID 37794185, 2023). "In vivo, PTPN2 deletion results in increased anti-tumor immunity, with Ptpn2 deficient CD8+ T cells displaying better cytotoxic activity and reduced exhaustion compared to wildtype cells." (PMID 38022587, 2023). "Its use in mice caused tumor hyperthermia, PTPN2 depletion, increased T cell infiltration into the tumor, and higher intratumoral IFN-γ and TNF-α levels." (PMID 35911672, 2022). "In tumors, PTPN2 affects tumor cells and tumor-associated cells, thereby influencing tumor progression." (PMID 36077422, 2022). "Along with increased proliferation, PTPN2 deficient mice also have enhanced cytotoxicity among Tim-3+ cells (a marker of the terminally exhausted state), and augmented anti-tumor function, tumor control, and anti-PD-1 responses." (PMID 35911672, 2022). "It has been reported that PTPN2 deficiency in T cells enhances the efficacy of cancer immuno-monitoring and over-metastatic tumor-specific T cells." (PMID 35461336, 2022). "Synchronously, inhibition of JAK/STAT pathway is relieved by deleting PTPN2, which promotes tumor susceptibility to CD8+ T cells depending on IFN‐γ, thus further amplifying adaptive immune responses." (PMID 34258164, 2021). "Taken together, these results point towards T‐cell‐specific PTPN2 deficiency promoting anti‐tumour activity in a setting where TRM cells are primarily responsible for immunosurveillance." (PMID 31803974, 2020). "Strikingly, the repression of tumour growth by PTPN2‐deficient HER‐2 CAR T cells persisted long after HER‐2 tumours had been eradicated, so that approximately half of all mice were alive for longer than 200 days with the remaining half succumbing to tumours." (PMID 31803974, 2020). "A recent CRISPR loss‐of‐function screen in tumour cells identified PTPN2 as a top‐hit for the recruitment of T cells and the sensitisation of tumours to anti‐PD‐1 therapy." (PMID 31803974, 2020).
tumor (continued). "Nevertheless, in the context of malignancies, such as colorectal carcinoma, increased inflammasome activity upon loss of PTPN2 had a benign effect via promotion of anti-tumor immune responses, which allowed more efficient tumor cell eradication." (PMID 32751912, 2020). "We found that the repression of tumour growth by PTPN2‐deficient CD8+ HER‐2 CAR T cells was accompanied by a marked increase in CD45+ CD8+ CD3+ mCherry+ CAR T‐cell abundance in tumours and the corresponding draining lymph nodes." (PMID 31803974, 2020). "Low PTPN2 protein expression was found in 50.2% of the tumours (110/219), gene copy loss in 15.4% (33/214)." (PMID 31025094, 2019). "PTPN2 protein expression correlated with ER positivity in the tumours (P = 0.0066) and borderline associated with PR expression (P = 0.058)." (PMID 30515568, 2019). "Low PTPN2 protein expression was associated with poor response to tamoxifen in the group of patients with tumours histologically graded as 2 or 3, suggesting a need for other types of treatment in this group." (PMID 30515568, 2019). "Loss of function analyses in patients with mutation/deletion of the PTPN2 gene and knock-out mouse models indicate that PTPN2 acts as a tumor suppressor in T-cell malignancies and as a regulator of inflammation and immunity." (PMID 26040922, 2015). "Additionally, transmission electron microscopy (TEM) analysis of mitochondria in subcutaneous tumors from ALK+ ALCL mouse xenograft models revealed that PTPN2‐deficient tumor cells exhibited an accumulation of swollen and damaged mitochondria." (PMID 40734623, 2025). "Thus, systemic inhibition of PTPN2/N1 causes proinflammatory remodelling of the TME to support anti-tumour immunity." (PMID 37794185, 2023). "Since Compound 182 also enhanced the TCR-induced activation and proliferation of Lck-Cre;Ptpn2fl/fl CD8+ T cells ex vivo we surmise that the enhanced repression of tumor growth may be attributed to the inhibition of PTP1B in PTPN2-deficient T cells." (PMID 37500611, 2023). "PTPN2 showed a positive correlation with tumor mutation burden in solid cancers." (PMID 38022587, 2023). "Furthermore, AC484 demonstrated additive growth inhibitory effects in Ptpn2-deficient or Ptpn1-deficient B16 tumour cells." (PMID 37794185, 2023). "AT3‐OVA tumours in mice treated with PTPN2‐deficient OT‐1 CD8+ T cells started to re‐emerge after 21 days, but survival was prolonged for as long as 86 days; by contrast, control mice achieved the maximum ethically permissible tumour burden (200 mm2) by 25 days." (PMID 31803974, 2020). "Likewise, PTPN2-deficient T cells were also able to markedly improve tumor therapy in syngeneic tumor models." (PMID 32726622, 2020). "Next, we determined whether PTPN2 deficiency might promote T‐cell‐mediated immunosurveillance and anti‐tumour activity in a different tumour setting." (PMID 31803974, 2020). "One research published recently noted that a deficiency of PTPN2 could enhance anti-tumor immunity and the therapeutic efficacy of CAR T cells to solid cancers." (PMID 32536826, 2020). "Moreover, consistent with the potential for increased homing, we found that PTPN2‐deficient CXCR3hi CAR T cells accumulated in HER‐2‐E0771 tumours within 3 days of adoptive transfer, prior to any effects on tumour burden." (PMID 31803974, 2020). "Moreover, even where tumours were evident in mice treated with PTPN2‐deficient OT‐1 T cells, tumour volumes were 10‐fold lower and this was accompanied by the increased tumour T‐cell infiltration." (PMID 31803974, 2020). "To explore whether the increased cell surface CXCR3 might contribute to the increased homing and anti‐tumour activity of PTPN2‐deficient CAR T cells, we sought to correct the increased CXCR3 expression." (PMID 31803974, 2020).
tumor (continued). "We found that PTPN2‐deficient HER‐2 CAR T cells expressed higher cell surface levels of CXCR3 in vitro prior to adoptive transfer as well as in vivo after CAR T cells had infiltrated tumours (Fig EV3C)." (PMID 31803974, 2020). "Indeed, we demonstrated that the homing and efficacy of PTPN2‐deficient CAR T cells was reliant on tumours expressing STAT‐1‐driven CXCR3 chemokines." (PMID 31803974, 2020). "Importantly, the doxycycline‐inducible overexpression of PTPN2 in HER‐2‐E0771 cells and the decreased CAR T‐cell recruitment abrogated the ability of PTPN2‐deficient CAR T cells to suppress tumour growth." (PMID 31803974, 2020). "Patients with NHG 1 tumours with low PTPN2 tended to have a higher risk for distant recurrence, indicating that PTPN2 loss might have a prognostic value in patients with NHG1, which is normally associated with good prognosis." (PMID 30515568, 2019). "We examined PTPN2 expression with respect to six immune cells frequently infiltrating tumors, including tumor-associated macrophages (TAMs), myeloid-derived suppressor cells (MDSCs), neutrophils, CD8+ T cells, regulatory T cells (Tregs), and natural killer (NK) cells." (PMID 29764444, 2018). "A previous analysis identified biallelic frameshift mutations in one of 69 PTCLs29, suggesting that PTPN2 could also function as a tumor suppressor in mature T cell malignancies." (PMID 29789628, 2018). "Loss of PTPN2 sensitizes the tumor to immunotherapy via IFNγ signaling." (PMID 29764444, 2018). "However, although the partial inactivation of PTP1B and/or PTPN2 may promote the development of immunogenic DCs and anti-tumor immunity, the complete loss of either PTP can impair DC maturation and function." (PMID 37500611, 2023). "Moreover, PTPN2 exerts a tumor-associated immunity function in other immune cells." (PMID 36077422, 2022). "Several other studies have identified genes that could be targeted to promote tumor immunotherapy; for example, the loss of Ptpn2 and Adar1 was found to improve antigen presentation and tumor sensitisation to anti‐PD‐1 blockade to improve immunotherapy, respectively." (PMID 34188916, 2021). "Thus, the question remains whether human PTPN2-deficient T cells expressing a tumor-specific CAR or TCR would similarly express increased exhaustion markers." (PMID 33425916, 2020). "Moreover, tumour‐infiltrating PTPN2‐deficient CD4+ and CD8+ effector/memory T cells were significantly more active, as assessed by the PMA/ionomycin‐induced production of markers of T‐cell cytotoxicity ex vivo, including interferon (IFN)‐γ and tumour necrosis factor (TNF)." (PMID 31803974, 2020). "To explore the cellular mechanisms by which PTPN2 deficiency might enhance immunosurveillance, we determined whether PTPN2 deletion might promote the tumour‐specific activity of adoptively transferred CD8+ T cells expressing the OT‐1 TCR specific for the ovalbumin (OVA) peptide SIINFEKL." (PMID 31803974, 2020). "We demonstrate that genetic silencing or pharmacological dual inhibition of protein tyrosine phosphatases PTPN1 and PTPN2 (PTPN1/N2) in NK cells significantly enhances anti-tumor cytolytic activity both in vitro and in vivo." (PMID 41986797, 2026). "PTPN2 inhibition (PTPN2i) increases HNSCC tumor cell STING by restoring IFNγ-STAT1-mediated induction of STING mRNA." (PMID 42069723, 2026). "Mice in the PTPN2 knockout group displayed a significantly reduced tumor growth rate and tumor size." (PMID 40734623, 2025). "Collectively, we demonstrated that PTPN2 was upregulated and played a critical role in promoting tumor growth and survival specifically in ALK+ ALCL." (PMID 40734623, 2025). "The PROTAC DU-14 acts as a dual degrader, targeting both PTP1B and TC-PTP (PTPN2), PTPs that are negative regulators of T-cell activation and tumour antigen presentation." (PMID 40941028, 2025). "PTPN2 depletion can significantly suppress tumor cell proliferation, induce apoptosis, and provoke cell cycle arrest." (PMID 40734623, 2025).
tumor (continued). "Next, we investigated the role of PTPN2 in tumor growth and survival by introducing control or PTPN2‐targeting sgRNAs into ALK+ ALCL cell lines using CRISPR/Cas9 technique." (PMID 40734623, 2025). "Intriguingly, the first‐in‐class PTPN2/N1 inhibitor AC484 shows a great anti‐tumor effect against ALK+ ALCL, providing a rationale for conducting clinical trials of AC484 on ALK+ ALCL patients." (PMID 40734623, 2025). "Here we have developed a tumor microenvironment responsive nanoplatform (H-MnO2(ISL + DOX)-PTPN2@HA, M(I + D)PH) for nano-herb and CRISPR codelivery to reduce chemoresistance." (PMID 38898493, 2024). "The T7EI assay results suggested significant genome disruption in the PTPN2 site in the tumor tissue." (PMID 38898493, 2024). "PTPN2‐deficient HER‐2‐targeting CAR-T cells exhibited augmented LCK‐dependent activation and notable suppression of tumor formation." (PMID 38918817, 2024). "Ptpn2 knockout in all hematopoietic cells leads to better tumour control and enhanced anti‐PD‐1 responses to B16 tumours." (PMID 39169517, 2024). "Protein tyrosine phosphatase non-receptor type 2 (PTPN2) is considered to be a new target for tumor immunotherapy, and deletion of PTPN2 in tumor cells can strengthen immune response by enhancing interferon-γ (IFN-γ)-mediated effects on antigen presentation." (PMID 38898493, 2024). "Evidence suggests that PTPN2 plays a key role in regulating the cell-intrinsic sensitivity of tumour cells to immunotherapy." (PMID 38334623, 2024). "In MC38 tumor-bearing mice, the PTPN2/PTP1B inhibitor ABBV-CLS-484 shows dose-dependent immune activation and reversible immune infiltration of in vivo tissues that is dependent on its administration status." (PMID 39065585, 2024). "Cells underwent gene editing to target PTPN2, which can greatly activate the antigen presentation effects and boost tumor immunity in vivo." (PMID 38898493, 2024). "The enhanced efficacy of immunotherapy following the loss of PTPN2 was associated with increased granzyme B+ cytotoxic CD8+ T cell and γδ T cell recruitment to tumours." (PMID 38334623, 2024). "Among the targets identified, deletion of the protein tyrosine phosphatase PTPN2 in tumor cells showed particular promise by enhancing the efficacy of immunotherapy through its effect on interferon-γ-mediated antigen presentation and growth suppression." (PMID 38362491, 2024). "The deletion of Ptpn2 sensitised B16 tumours to immunotherapy, whereas PTPN2 overexpression rendered cells resistant." (PMID 38334623, 2024). "Evidence for cancer cell-intrinsic roles for PTPN1 and PTPN2 in the development or suppression of tumour growth has emerged." (PMID 38334623, 2024). "Previous studies have shown that the deletion of PTPN2 in tumor cells can enhance anti-tumor immunity by promoting IFN/JAK/STAT-1 signaling to drive T cell recruitment and MHC-I-dependent antigen presentation." (PMID 37500611, 2023). "PTPN2 was found to be involved in immune infiltration and played an important role in immune-tumor interaction." (PMID 37884566, 2023). "The enhanced anti-tumor immunity in immunogenic tumors can be ascribed to the inhibition of PTP1B/PTPN2 in T cells, whereas in cold tumors, Compound-182 elicited direct effects on both tumor cells and T cells." (PMID 37500611, 2023). "Nevertheless, we and others have shown that the deletion of either PTP1B or PTPN2 in T cells can markedly enhance anti-tumor immunity." (PMID 37500611, 2023). "Next, we evaluated the expression of PTPN2 in paired tumorous and normal samples and the results indicated that PTPN2 was differentially expressed in normal and tumor tissues in 13 types of cancer and was generally upregulated in tumor tissues." (PMID 37884566, 2023). "AC484 also enhanced immune control of Ptpn2/n1-null and control tumours to a similar extent, which indicated that PTPN2/N1 inhibition in immune cells is sufficient to drive efficacy." (PMID 37794185, 2023).
tumor (continued). "Preclinical studies have established the therapeutic potential of targeting PTP1B or PTPN2 for the promotion of anti-tumor immunity to combat cancer." (PMID 37500611, 2023). "Of note, the observed increase in abundance of tumor-infiltrating granzyme B-expressing CD8+ T cells is consistent with the phenotype previously reported for Ptpn2-null B16F10 tumors." (PMID 36968224, 2023). "Consistent with our results showing an additive effect of dual PTPN2/N1 inhibition in tumour cells, AC484 increased the expression of CD69 in PTPN2-deficient or PTPN1-deficient T cells." (PMID 37794185, 2023). "Beyond their roles in T cells, PTP1B and PTPN2 also have cell autonomous roles in tumors, by directly influencing tumor growth, as well as the ability of tumors to interact with immune cells." (PMID 37500611, 2023). "Our findings establish the potential for small molecule inhibitors of PTP1B and PTPN2 to enhance anti-tumor immunity and combat cancer." (PMID 37500611, 2023). "We next evaluated the tumour and immune-mediated effects of systemic PTPN2/N1 inhibition and their relative contributions to anti-tumour efficacy in vivo." (PMID 37794185, 2023). "Collectively, these findings and the results of the current study suggest an important role for PTPN2 in many cancer types, with potentially oncogenic and tumor suppressor functions." (PMID 36968224, 2023). "PTPN2 was then systematically correlated with immunological signatures in the AML tumor microenvironment and its differential expression was verified using clinical samples." (PMID 37884566, 2023). "The inhibition of protein tyrosine phosphatases 1B (PTP1B) and N2 (PTPN2) has emerged as an exciting approach for bolstering T cell anti-tumor immunity." (PMID 37500611, 2023). "Experiments in mice showed that Ptpn2 deletion enhances immune-mediated tumor control by sensitizing tumors to cytotoxic T cell killing and enhancing anti-tumor responses of T cells." (PMID 38022587, 2023). "Ptpn2-mediated dephosphorylation of Stat1 and Jak1 negatively regulates signaling induced by IFNγ, a potent inhibitor of tumor growth via stimulation of the antitumor immune response." (PMID 36968224, 2023). "Genetic ablation of PTPN2 or PTPN1 in tumour cells augments signal transduction from type I and type II IFNs, increasing downstream effects, including cell growth arrest, increased production of immune cell chemoattractants and increased antigen presentation." (PMID 37794185, 2023). "Owing to the importance of PTPN2/N1 in tumour and immune cells and the high homology of their active sites, we sought to discover a PTPN2/N1 small-molecule inhibitor that targets these two phosphatases." (PMID 37794185, 2023). "We have shown previously that the combined deletion of PTPN2 in AT3 tumor cells and T cells results in a greater repression of tumor growth than deleting PTPN2 either in tumor cells or T cells." (PMID 37500611, 2023). "The expression of four methylated transferases (DNMT1, DNMT2, DNMT3A and DNMT3B) in various tumor types was significantly correlated with the expression of PTPN2." (PMID 37884566, 2023). "We found significant correlations between PTPN2 expression and stemness score, and tumor heterogeneity." (PMID 37884566, 2023). "PTPN1 and PTPN2 inhibitors have been developed and have become emerging means to enhance T cell anti-tumor immunity." (PMID 37884566, 2023). "By contrast, the repression of tumor growth in Mx1-Cre;Ptpn2fl/fl mice in which PTPN2 was deleted throughout the hematopoietic compartment was accompanied by inflammation and overt morbidity." (PMID 37500611, 2023). "Ptpn2/n1-null tumours grew at the same rate as control tumours in mice receiving only GVAX, a result consistent with our previous findings." (PMID 37794185, 2023). "For example, phosphatase PTPN2 was identified as a novel immunotherapeutic target in the first in vivo CRISPR screening in tumor cells." (PMID 37964355, 2023).